HOTAIR (HOX transcript antisense RNA)
Diseases named in the same sentence as HOTAIR in open-access papers (continued):
Sharing a sentence is not in itself a finding about the gene and the disease.
cancer (continued). "Additionally, lncHUB2 identified tissues where HOTAIR is highly expressed, especially in specific cancer types." (PMID 36869839, 2023). "HOTAIR-silencing resulted in a decrease in matrix metalloproteinases (MMPs, which promote invasion and migration) expression and an increase in HOXA5 levels (a tumor suppressor) in cell lines, suggesting HOTAIR acts through the regulation of expression of cancer-related genes." (PMID 37370745, 2023). "Moreover, YTHDC1 levels regulate HOTAIR-induced pro-metastatic effects in cancer cells, as proven by overexpression and knock-down experiments." (PMID 37308974, 2023). "It has been observed that lncRNA HOTAIR expression and cancer metastasis are related." (PMID 37007957, 2023). "Through systematic review and bioinformatics analysis, we found that HOTAIR was involved in the regulation of cancer cell apoptosis, cell proliferation, and the induction of cell cycle arrest, EMT, migration, invasion, metastasis, and resistance in gastrointestinal malignancies." (PMID 36924407, 2023). "DEGs were involvedin the molecular mechanism of cancer, autophagy, and HOTAIR." (PMID 37581432, 2023). "This suggests that lncRNA HOTAIR downregulation might also reduce TGF-β1 secretion from cancer cells." (PMID 38070058, 2023). "Several lncRNAs, such as MALAT1, HOTAIR, PVT1, NEAT1, ANRIL, and SPRY4-IT1, have recently been identified, particularly in cell lines, liquid biopsy, and tissue biopsy samples and have been associated with cancer pathogenesis." (PMID 37424727, 2023). "Notably, the HOTAIR-induced modulation of PRC2-mediated epigenome causes a reprogramming of gene expression that resembles that of embryonic fibroblasts and triggers cancer cell invasiveness." (PMID 37308974, 2023). "HOTAIR plays an important role in cancer biology and deserves further study." (PMID 36924407, 2023). "Many studies have reported the abnormal expression of HOTAIR in cancer tissue." (PMID 36980864, 2023). "HOTAIR is significantly upregulated in many cancer types, including BC tissue." (PMID 36294743, 2022). "Since HOTAIR is known to reprogram chromatin status and alter chromatin modifications to promote cancer metastasis, we performed an Assay for Transposase-Accessible Chromatin using sequencing (ATAC-seq) to assess genome-wide changes in the chromatin landscape induced by HOTAIR overexpression." (PMID 36579891, 2022). "Previous studies established that HOTAIR was an oncogenic factor for OS, promoting in vitro proliferation, metastasis, cisplatin resistance, inhibition of apoptosis, and cell cycle arrest in cancer cells." (PMID 35435107, 2022). "Together, our results support a mechanism where YTHDC1 interaction specifically at m6A783 leads to repression of HOTAIR genomic targets, and that this direct action causes further gene expression changes, cumulatively promoting HOTAIR- and m6A-dependent cancer cell phenotypes." (PMID 36441764, 2022). "HOTAIR is a well-studied oncogenic lncRNA in various cancers." (PMID 36471329, 2022). "This could indicate that HOTAIR acts as an antioxidant regulator lncRNA and prevents the cancer cell from surpassing the threshold ROS level that would activate apoptosis." (PMID 36077530, 2022). "However, apoptosis was inhibited by caspase-2 silencing in HOTAIR knockdown models revealing its significance in inducing apoptosis by targeting HOTAIR in cancer." (PMID 36171196, 2022). "Pharmacological inhibitors of EGFR and NF-κB signaling pathways as well as modulation of ProT and HOTAIR expression may be further explored for ameliorating cachexia in cancer patients undergoing chemotherapy." (PMID 36471329, 2022). "Interestingly, some of these lncRNAs (such as ANRIL, H19, and HOTAIR) are also dysregulated in cancer, creating a link between the ncRNA expression profile and cancer risk in obese people, as reported by Yau and colleagues." (PMID 36012617, 2022).
cancer (continued). "We summarized the various mechanisms by which HOTAIR leads to tumor resistance and conclude that HOTAIR may play an important role in cancer therapy in the future." (PMID 36100611, 2022). "Both MALAT1 and HOTAIR have been proposed as therapeutic targets in cancer." (PMID 36233046, 2022). "This concluded that HOTAIR expression was upregulated approximately three-fold in cancer tissues." (PMID 35435107, 2022). "Having shown the high expression of HOTAIR in GC and IM, we considered whether HOTAIR might be used as a noninvasive biomarker for cancer detection." (PMID 35347094, 2022). "During the past years, MEG3 and HOTAIR expression has been investigated in various cancer types; however, the precise molecular mechanism by which these lncRNAs promote tumorigenesis remains unclear." (PMID 35186192, 2022). "In addition, some chemical compound that interrupts the HOTAIR—EZH2 interaction are found to inhibit cancer cell invasion and migration, which was thought to be a potential approach for targeted therapy of cancers." (PMID 36533073, 2022). "Recent studies revealed that HOTAIR is involved in the modulation of the apoptotic pathway in cancer cells, which may be related to chemotherapy resistance." (PMID 36100611, 2022). "We are also able to ascribe the potential impact of HOTAIR as intrinsic to cancer cells." (PMID 36579891, 2022). "Currently, only three studies have addressed the role of miR-203′s link with HOTAIR in cancer." (PMID 36233075, 2022). "The involvement of HOTAIR in cancer progression and NF-κB signaling suggests that HOTAIR may also be an important player in cancer cachexia." (PMID 36471329, 2022). "Similarly, monitoring OS cell lines revealed elevated HOTAIR levels in both cancer cells compared to those in HFOB1.19 cells." (PMID 35435107, 2022). "Both wild-type (WT) and the mutant form of HOTAIR were expressed at similar levels averaging approximately 5,000 to 6,000 copies of HOTAIR per cell, resembling the high levels of HOTAIR observed in samples from cancer patients." (PMID 36441764, 2022). "As most studies have used nuclear extracts to study the role of HOTAIR in cancer cell lines, it might be interesting to have a look at the role that the cytoplasmic HOTAIR fraction performs in these cell lines." (PMID 35087108, 2022). "HOTAIR has been proved to be highly expressed in many cancers and regarded as a tumor gene." (PMID 35093153, 2022). "Thus, we demonstrate that HOTAIR plays a critical role in skeletal muscle atrophy in cisplatin-induced cancer cachexia." (PMID 36471329, 2022). "HOTAIR promotes the proliferation, invasion, and metastasis of human cancer cells." (PMID 35619625, 2022). "Although HOTAIR has been described as an oncogene for various cancers, its physiological functions in HOTAIR-expressing tissues are largely unknown." (PMID 35905723, 2022). "Of the currently designated m6A reader proteins, we have previously shown that hnRNP A2/B1, a proposed non-canonical reader lacking the m6A-binding YTH domain, can interact with HOTAIR to regulate its chromatin and cancer biology mechanisms by promoting HOTAIR interactions with target mRNAs." (PMID 36441764, 2022). "LncRNAs may serve as biomarkers of cancer, such as nuclear enriched abundant transcript 1 (NEAT1), HOX Transcript Antisense RNA (HOTAIR), metastasis-associated lung adenocarcinoma transcript 1 (MALAT-1), H19." (PMID 36034367, 2022). "For example, lncRNA HOTAIR is involved in some cancer malignant progression." (PMID 36033389, 2022). "Moreover, the relation of chromatin-associated RNAs with cancer progression has been documented in many instances, such as PVT1, H19, MALAT1, and HOTAIR (for a recent review, see reference 45)." (PMID 36445136, 2022). "As HOTAIR may play roles in inflammation and immune responses, we investigated further the role of HOTAIR in the expression of pro-inflammatory cytokines that contribute to cancer cachexia." (PMID 36471329, 2022).
cancer (continued). "Therefore, HOTAIR played a promotive role in cancer cell proliferation, invasion, metastasis, and chemoresistance." (PMID 35656022, 2022). "Importantly, downregulation of p21Cip1/Waf1 has been mechanistically involved in HOTAIR-dependent cancer radioresistance." (PMID 35456025, 2022). "Interestingly, several genes were known to be regulated by the TGFβ pathway (e.g., BMF, COL4A4) and/or expressed in several cancers (e.g., HOTAIR, MRC2, POSTN, SPARC)." (PMID 34830779, 2021). "Besides, HOTAIR is involved in non-cancer pathological processes, including diabetic cardiopathy, Parkinson’s disease, and rheumatoid arthritis." (PMID 34073224, 2021). "It was reported that the expression of HOTAIR in cancer cells can be enhanced by osteopontin." (PMID 33670447, 2021). "Meanwhile, datasets mining also found the higher expression of HOTAIR in cancer tissues." (PMID 34320988, 2021). "In addition, HOTAIR is able to reprogram the chromatin state to promote cancer metastasis in a polycomb repressive complex 2 (PRC2)-dependent manner." (PMID 33747903, 2021). "HOTAIR expression, functions, and prognostic and therapeutic potential in different human cancers." (PMID 34367966, 2021). "Overexpressed HOTAIR could promote the occurrence of drug resistance in cancers and reduce the sensitivity of cancer cells to chemoradiotherapy, indicating HOTAIR may be a vital prognostic factor for predicting drug resistance of tumors." (PMID 34367966, 2021). "Moreover, the involvement of HOTAIR in cancer progression and response to standard chemotherapy, possibly promoting mesenchymal stem cell formation, has been highlighted." (PMID 34638965, 2021). "Moreover, silibinin targets lncRNAs, such as ZFAS1 and HOTAIR, which are identified as oncogenic factors in several cancers." (PMID 33805687, 2021). "Due to the important role of HOTAIR in tumors, several studies have reported that HOTAIR knockdown may be a potent approach for cancer treatment." (PMID 34367966, 2021). "Taken together, the level of HOTAIR is higher in drug-resistant cancer cells and tissues." (PMID 34367966, 2021). "LncRNAs like MALAT1 and HOTAIR which are associated with metastasis are over expressed in cancer and MEG3 and PTENP1 which inhibit cell proliferation and migration are downregulated in cancer." (PMID 34858475, 2021). "Additionally, certain HOXATs, including HOXA-AS2, HOXB-AS1, and HOTAIR possibly exerted distinct prognostic effects across the various cancer types." (PMID 34805277, 2021). "Recently, HOTAIR has been reported to be elevated in CSCs derived from various malignant tumors." (PMID 34539782, 2021). "HOTAIR is regarded as an oncogene involved in both the initiation and progression of cancer." (PMID 34322392, 2021). "The direct or indirect block/inhibition of HOTAIR may represent a new and effective therapeutic strategy for rare cancer and tumors." (PMID 34576322, 2021). "HOTAIR is a well-established critical player with oncogenic roles in cancer biology." (PMID 33446111, 2021). "In fact, different studies showed that the direct or indirect block/inhibition of HOTAIR may represent a new and effective cancer therapeutic strategy." (PMID 34208964, 2021). "Thus, HOTAIR seems to serve as a prognostic factor for survival, as well as a biomarker for identifying molecular subtypes in cancer." (PMID 34722321, 2021). "Interestingly, a recent studies reported that the late-stage osteogenic marker osteopontin (OPN), which is an extracellular matrix protein secreted by osteoblasts and osteocytes, can transcriptionally activate and increase HOTAIR expression in cancer cells." (PMID 33461171, 2021). "Thus, it is possible to modulate the HOXD gene by modulating HOTAIR levels, which has implications in cancer therapy." (PMID 34722321, 2021).
cancer (continued). "MiR-141 can interact with HOTAIR by combining directly with the 3′UTR of HOTAIR in cancer cells, also modulating the expression of the spindle and kinetochore-associated complex subunit 2(SKA2) gene, involved in the maintenance of the metaphase plate and/or spindle checkpoint silencing." (PMID 33540611, 2021). "Osteopontin was reported to regulate HOTAIR in cancer cells." (PMID 33446111, 2021). "HOTAIR is an oncogenic lncRNA reported in colon, liver, breast, and other cancers." (PMID 34820419, 2021). "HOTAIR knockdown in the TRAIL-resistant PANC-1 cancer cells restored apoptotic cell death." (PMID 34178644, 2021). "In fact, HOTAIR has the potential to be an effective therapeutic target for many types of cancer, where abnormal HOXD expression has been found to be associated with cancer progressions, such as cancers in breast, stomach, colon, cervix, lung, and liver." (PMID 34722321, 2021). "To determine the mechanism by which HOTAIR regulates the expression of genes associated with cartilage catabolism and anabolism in OA, we investigated WIF-1 due to its known interactions with HOTAIR in cancer progression." (PMID 32650720, 2020). "Besides, HOTAIR, a well-known oncogenic lncRNA, was reported to be frequently overexpressed in various human cancers, linking to poor prognosis, metastasis, and recurrence." (PMID 33363573, 2020). "Thus, the importance of HOTAIR in cancer biology has sparked interest by using HOTAIR as a biomarker and potential therapeutic target." (PMID 32248643, 2020). "In addition to HOXD1-AS1, HOTAIR is a well-studied lncRNA that is upregulated in a variety of cancer types." (PMID 33291485, 2020). "The lncRNA HOTAIR has been extensively investigated in cancer pathogenesis and progression." (PMID 32486876, 2020). "Similar to radiotherapy and hormone therapy, HOTAIR activity could deregulate the mechanism of several commonly used chemotherapeutic such as carboplatin and gemcitabine in breast and other types of cancer." (PMID 32245498, 2020). "Furthermore, elevated HOTAIR expression was detected in patients that had high histological grade tumors or advanced clinical stage cancer." (PMID 32117729, 2020). "There is a new body of evidence that HOTAIR is also overexpressed in a number of cancers, which suggests that HOTAIR may play a role in SHH dysregulation in cancer." (PMID 33303026, 2020). "Moreover, HOTAIR is able to physically interact with the miR34 promoter to silence miR34a in cancer stem cells (CSCs) from BC cells." (PMID 32397382, 2020). "Although HOTAIR is also reported to contribute attainment of cellular phenotypes, its role is generally defined in means of correlations with aggressiveness traits of cancer cells." (PMID 32650779, 2020). "Given the fact that HOTAIR is a pivotal regulator and promising target, modifications of HOTAIR may have profound influence on cancer progression." (PMID 32209098, 2020). "It is also possible that the lncRNAs differentially expressed after 5-AzaC exposure may be involved in a 5-AzaC drug resistance mechanism, as shown for human cancer-related lncRNAs such as HOTAIR and XIST69–71." (PMID 33299037, 2020). "Moreover, the expression level of HOTAIR is proved to be correlated with cancer progression and unfavorable clinical outcomes of cancer patients in most solid cancers." (PMID 32209098, 2020). "Several reports have indicated the aberrant HOTAIR expression in many cancers." (PMID 32785167, 2020). "HOTAIR was originally identified as a cancer-related lncRNA." (PMID 31974341, 2020). "HOTAIR was initially described as an epigenetic factor that functions in chromosomal remodeling and coordinates the recruiting of polycomb repressive complex 2 to gene promoters regulating in this way the cancer epigenome." (PMID 32466537, 2020). "The most prolific lncRNAs, with ≥16 recorded cancer types, are HOTAIR, MALAT1, MEG3 and H19." (PMID 32024996, 2020). "Various studies have reported on the contribution of HOTAIR to cancer pathogenesis." (PMID 32117729, 2020).
cancer (continued). "It is suggested that the inhibitory effect of PTCSC3 on the proliferation of cancer cells may be related to HOTAIR." (PMID 32848755, 2020). "Accumulating lines of evidence have proven that lncRNAs could be targets for cancer diagnosis and may be suitable biomarkers, such as HOTAIR, H19, and XIST." (PMID 32785606, 2020). "Similarly to other lncRNAs, HOTAIR has shown to recruits chromatin-modifying proteins and to affect cancer epigenome modulation." (PMID 32154165, 2020). "HOTAIR is a famous cancer-related lncRNA and it is highly expressed in NSCLC and SCLC." (PMID 32149133, 2020). "It has been suggested that HOTAIR promotes cancer invasiveness and metastasis by the induction of a more embryonic-like state, which leads to increased resistance to known therapies and is a marker for poor prognosis in almost all cancer types." (PMID 32231885, 2020). "With loss of BRCA1, HOTAIR competitively interacts with EZH2 via similar binding site to BRCA1, culminating in hypermethylation of H3K27me3 and PRC2 occupancy of the corresponding target sites in the breast luminal epithelial cancer cells." (PMID 32245498, 2020). "HOX antisense intergenic RNA (HOTAIR) is deregulated in diverse cancers and could be an independent and powerful predictor of eventual metastasis and death." (PMID 30764859, 2019). "Genistein downregulates the expression of HOTAIR at the transcription level in several cancers." (PMID 31208095, 2019). "The mechanism by which HOTAIR regulates gene expression has been elucidated; it has been found that HOTAIR acts as scaffold of various different complexes involved in different types of human cancers." (PMID 30866496, 2019). "Among all, lncRNA HOTAIR was found to participate in cancer metastasis and chemoresistance." (PMID 30429228, 2019). "HOTAIR could also regulate cancer proliferation as well as metastasis, and confer to tamoxifen resistance." (PMID 30429228, 2019). "In addition, HOTAIR overexpression attenuated the inhibitory effects of PTCSC3 overexpression on cancer cell proliferation (P<0.05)." (PMID 31171714, 2019). "In addition, knock-down of HOTAIR in cancer cells is able to induce E-cadherin expression and vimentin and beta-catenin repression, suggesting that CAFs promote EMT and metastasis by activating HOTAIR expression." (PMID 31072041, 2019). "The first 3 burst words after 2014 were “cancer stem cell”, “HOTAIR” and “UCA1”." (PMID 31143372, 2019). "HOTAIR is a well-characterized oncogenic lncRNA in cancer biology." (PMID 31113870, 2019). "Importantly, the knockout of HOTAIR inhibits cell proliferation and migration, and induces apoptosis and cell cycle arrest in various cancer types." (PMID 30669611, 2019). "In addition, numerous experimental evidences have focused the attention on the potential role of HOTAIR as circulating marker in cancer patients and as potential therapeutic target." (PMID 31137568, 2019). "The multiple roles of HOTAIR and UCA1in drug resistance may offer big opportunities for the targets of cancer therapy." (PMID 31143372, 2019). "Therefore, high HOTAIR expression can predict an unfavorable clinical outcome in different types of cancers and possibly ethnic groups using different extraction methods." (PMID 31195674, 2019). "Therefore, PTCSC3 as the upstream inhibitor of HOTAIR should also interact with other factors to inhibit the inhibitor effects of HOTAIR down-regulation (as a result of PTCSC3 overexpression) on cancer cell migration and invasion." (PMID 31171714, 2019). "Moreover, HOTAIR promotes proliferation, survival, invasion, metastasis, and drug resistance in the cancer cells." (PMID 31281803, 2019). "Thus, more clinical trials on these cancers would enable us to better assess the relationship between HOTAIR expression and cancer patients’ survival." (PMID 31195674, 2019). "HOTAIR expression level is increased in multiple cancers, including BC, LC, GC, and NB." (PMID 31480503, 2019).